RABEPK (Rab9 effector protein with kelch motifs)
Description:
Rab9 effector required for endosome to trans-Golgi network (TGN) transport.
Synonyms: RAB9P40; bA65N13.1; p40
Tractability: Antibody: UniProt places it where antibodies can reach, with high confidence. PROTAC: ubiquitination databases record sites on it; its protein half-life has been measured.
Gene: Protein-coding gene on chromosome 9 (125,200,538 to 125,234,161, forward strand). Ensembl gene ENSG00000136933.
Subcellular location: Cytoplasm; Endosome membrane
Subcellular location (Human Protein Atlas): Vesicles
Pathways (Reactome):
Vesicle-mediated transport: Retrograde transport at the Trans-Golgi-Network
Gene Ontology:
Molecular function: protein binding
Biological process: receptor-mediated endocytosis
Cellular component: endosome membrane; cytosol; endosome; trans-Golgi network membrane; transport vesicle; cytoplasm
Genetic constraint (gnomAD): Loss-of-function variants: 26 observed, 33.67 expected, observed/expected ratio (o/e) 0.77, 90% interval 0.56 to 1.07. The upper end of that interval is the gene's LOEUF score, 1.07, which puts it in group 4 of 6, group 1 being the genes least tolerant of losing a copy. Missense variants: 427 observed, 464.73 expected, observed/expected ratio (o/e) 0.92, 90% interval 0.85 to 1. Synonymous variants: 165 observed, 173.52 expected, observed/expected ratio (o/e) 0.95, 90% interval 0.84 to 1.08.
Homologues: Orthologues: chimpanzee RABEPK (99% identical), macaque RABEPK (94% identical), pig RABEPK (85% identical), rabbit RABEPK (84% identical), guinea pig RABEPK (83% identical), dog RABEPK (81% identical), rat Rabepk (80% identical), mouse Rabepk (79% identical), tropical clawed frog rabepk (50% identical), zebrafish rabepk (46% identical). Paralogues in human: HCFC1 (28% identical), HCFC2 (26% identical), LZTR1 (25% identical), FBXO42 (21% identical), KLHDC10 (21% identical), KLHDC2 (21% identical), KLHDC4 (21% identical), KLHDC1 (19% identical), KLHDC3 (19% identical), KLHDC9 (19% identical).
Diseases named in the same sentence as RABEPK in open-access papers:
RABEPK is named in the same sentence as 6 diseases in open-access papers, as found by Europe PMC text mining. Sharing a sentence is not in itself a finding about the gene and the disease. The quoted sentences say what the papers report.
opioid use disorder (2 papers, 2023). A substance-related disorder that involves the recurring use of opioids despite negative consequences. "RABEPK (Rab9 effector protein with Kelch motifs) belonged to a small set of genes emerging in genome-wide association studies of opioid use disorder." (PMID 37672513, 2023). "We did not search for disorders linked to RABEPK, however Rachel L. Kember’s study This gene was discovered to be linked to opioid use disorder (OUD), and previous research has shown a link between OUD and BD." (PMID 37860165, 2023).
bipolar disorder (1 paper, 2023). A disorder of the brain that causes unusual shifts in mood, energy, activity levels and the ability to carry out day-to-day tasks. "Potential candidate genes for bipolar disorder with metabolic syndrome were found in 5 candidate genes (AP1G2, C1orf54, DMAC2L, RABEPK and ZFAND5), all of which have diagnostic significance." (PMID 37860165, 2023).
Stroke (1 paper, 2020). Sudden impairment of blood flow to a part of the brain due to occlusion or rupture of an artery to the brain. "Thus, intra-arterial treatment with exosomes of miR-133b+ BMSCs released exosomes from astrocytes, possibly by downregulating RABEPK expression, and improved stroke recovery together with neurite regeneration." (PMID 32962207, 2020).
RABEPK also shares sentences with these, for which no sentence is quoted: melanoma (1 paper); metabolic syndrome (1); tuberculosis (1).